PLK1 (polo like kinase 1)
Diseases named in the same sentence as PLK1 in open-access papers (continued):
Sharing a sentence is not in itself a finding about the gene and the disease.
breast carcinoma (continued). "The multivariate logistics regression analysis was applied to evaluate the performance of the panel of 3 genes (CDK1,CDC25A and PLK1) as biomarkers for breast cancer prediction." (PMID 40081286, 2025). "Our study further revealed that miR‐195‐5p transfection led to the downregulation of CCND3, CDK4, and PLK1 in all studied breast cancer cell lines." (PMID 40548926, 2025). "We evaluated the potential of eCas12f1 as a cancer therapy by targeting PLK1 in breast cancer (SKBR-3) cell lines." (PMID 39809780, 2025). "CDK1, CDC25A, and PLK1 were upregulated in breast cancer compared to normal tissues, based on BRCA data analysis." (PMID 40081286, 2025). "n this study, we utilized systematic pharmacological tools and bioinformatics to demonstrate that DHIE, the main active ingredient in AKH, inhibits breast cancer by suppressing the expression of PLK1 in breast cancer cells." (PMID 40093330, 2025). "PLK1, a kinase essential for spindle formation and chromosome separation, is often overactivated in breast cancer, promoting tumour growth." (PMID 40081286, 2025). "G2/M checkpoint‐related genes are enriched in breast cancer bone metastases, and PLK1 expression is upregulated and promotes tumor cell proliferation." (PMID 39949984, 2025). "Based on various bioinformatics, in silico docking and in vitro MCF7 cell line study reveals that the C. urens fruit extract targets the genes of cell cycle i.e. CDK1,CDC25A, and PLK1 in breast cancer." (PMID 40081286, 2025). "eCas12f1 induced cell death in breast cancer cells by disrupting PLK1 and notably eCas12f1 effectively disrupted cancer-specific genes by recognizing BRAF mutations in the malignant melanoma cells." (PMID 39809780, 2025). "Both CDC25A and PLK1 serve as potential therapeutic targets and biomarkers, offering promise for personalized breast cancer treatments by halting uncontrolled cell growth." (PMID 40081286, 2025). "Targeting CDK1, CDC25A, and PLK1 offers a promising therapeutic strategy in breast cancer due to their pivotal roles in cell cycle regulation." (PMID 40081286, 2025). "Studies have shown that PLK1 can modulate development of HER2-driven breast cancers affecting chromosomal instability and cellular growth rate." (PMID 40700427, 2025). "The bioinformatics analysis identified CDK1, CDC25A, and PLK1 as pivotal genes regulating cell cycle progression and breast cancer tumorigenesis." (PMID 40081286, 2025). "For instance, an EpCAM-targeting aptamer fused to a siRNA against Polo-like kinase 1 (PLK1) effectively reduced tumor burden in breast cancer models." (PMID 41153385, 2025).
breast carcinoma (continued). "Although we validated key hits in patient-derived xenograft (PDX) models of breast and multiple breast cancer cell lines, the generalizability of these findings across all PLK1-driven cancers remains to be further tested in a broader panel of tumor types." (PMID 40347943, 2025). "Targeting multiple genes, such as CDK1, CDC25A, and PLK1, effectively induces cell cycle arrest, offering a promising therapeutic strategy for breast cancer." (PMID 40081286, 2025). "Episesamin, a major phytoconstituent of C. urens, was found to target CDK1, CDC25A, and PLK1-key cell cycle regulators in breast cancer." (PMID 40081286, 2025). "The publicly available bc-GenExMiner V4.8 web–based tool was employed to investigate the specific expression patterns of CHEK1 and PLK1 in TNBC compared to other breast cancer subtypes." (PMID 39473450, 2024). "Knockdown of PLK1 in breast carcinoma cell lines suppressed cell viability, colony formation, and invasion, while PLK1 overexpression attenuated the inhibitory effects of SAMD5 overexpression." (PMID 39524172, 2024). "WB analysis showed that PLK1 and RhoGDI1 were expressed in all breast cancer cell lines and HeLa cells." (PMID 38355643, 2024). "PLK1 is a key regulator of mitotic cell division and has been shown to be overexpressed in several human cancers, including breast cancer." (PMID 39596199, 2024). "Targeting the SAMD5/PLK1 axis offers a promising therapeutic strategy for addressing aggressive breast cancers." (PMID 39524172, 2024). "We measured the response of the five HER2+ breast cancer cell lines grown in fibroblast-conditioned medium to the ATP-competitive PLK1 inhibitor GSK461364 alone or in combination with lapatinib." (PMID 39513002, 2024). "PLK1 has been found to be overexpressed in breast cancer, with up to 92% of TNBC patients showing overexpressed levels of this protein." (PMID 38606093, 2024). "We also verified the elevated expression levels of PLK1 in the blood of breast cancer patients compared to normal subjects." (PMID 39596658, 2024). "The findings presented here not only enhance our understanding of breast cancer biology but also highlight the potential of the SAMD5/PLK1 axis as a therapeutic target." (PMID 39524172, 2024). "Compared to monoculture, fibroblast-conditioned medium increased the expression of plasminogen activator inhibitor-1 (PAI1) and cell cycle regulator polo like kinase 1 (PLK1) in lapatinib-treated breast cancer cells." (PMID 39513002, 2024). "As an additional approach to exploit therapeutic vulnerabilities in fibroblast-protected breast cancer cells, we explored targeting PLK1 that predicted lapatinib response in cancer cells exposed to fibroblast-conditioned medium." (PMID 39513002, 2024). "Overexpression of PLK1 in breast cancer is thought to result in aberrant cell division and genomic instability." (PMID 38606093, 2024). "ELISA results further demonstrate that PLK1 expression is elevated in the blood of breast cancer patients compared to healthy controls." (PMID 39596658, 2024). "These past studies serve to partially validate our significant pathway findings and lend credence to ongoing research into PLK1 inhibition as a potential treatment for patients with ER+ breast cancer." (PMID 39057065, 2024). "Given the upregulation of PLK1 in breast cancer, PLK1 knockdown was achieved in two TNBC cell lines (MDA-MB-231 and HCC1937) by introducing small interfering RNA against PLK1 (si-PLK1-1/2/3) and validated using immunoblotting." (PMID 39524172, 2024). "Researchers found that PLK1 inhibition suppressed the proliferation of breast cancer cells and increased their sensitivity to radiation and pabocinib." (PMID 39834939, 2024). "As previously reported, PLK1 served as a biomarker for the prognosis of early-stage breast carcinoma." (PMID 39524172, 2024). "Mechanistic studies indicated that SAMD5 negatively correlated with PLK1, a gene overexpressed in breast carcinoma, especially in triple-negative subtypes." (PMID 39524172, 2024).
breast carcinoma (continued). "This study investigated the potential of onvansertib, a highly specific inhibitor of polo-like kinase 1 (PLK1), to enhance the efficacy of alpelisib in preclinical models of HR+ breast cancer." (PMID 39409880, 2024). "Taken together, these studies position PLK1 as a promising combination therapy partner to enhance treatment response to multiple anticancer treatments in breast cancer, including chemotherapy, estrogen- and HER2-targeted therapy." (PMID 39513002, 2024). "In this study, we have investigated the therapeutic potential of the PLK1 inhibitor onvansertib in combination with the FDA-approved PI3Kα inhibitor alpelisib for advanced HR+ breast cancer." (PMID 39409880, 2024). "Previous work has demonstrated that polo-like kinase 1 (Plk1) is highly expressed in breast cancer, and high Plk1 expression predicts better survival in some subtypes." (PMID 39007996, 2024). "PLK1 has emerged as a promising therapeutic target in breast cancer, particularly in TNBC, where successful molecular-targeted therapies are currently lacking." (PMID 39473450, 2024). "Our preclinical studies demonstrate the synergistic efficacy of the PI3Kα inhibitor alpelisib and the PLK1 inhibitor onvansertib in PIK3CA-mutant HR+ breast cancer cell lines and PDXs that are resistant to ET and palbociclib." (PMID 39409880, 2024). "Preclinical studies have shown that genetic and pharmacologic blockade of PLK1 in HER2+ breast cancer cells restored sensitivity to the anti-HER2 antibody-drug conjugate TDM1." (PMID 39513002, 2024). "To confirm the effect of the interaction between endogenous PLK1 and RhoGDI1 on cancer cell migration and invasion, we first assessed their expression in human breast cancer and HeLa cervical cancer cells." (PMID 38355643, 2024). "Inhibition of PLK1 decreased radiation-induced ROS and autophagy levels, thereby enhancing the sensitivity of breast cancer cells to radiation." (PMID 39596658, 2024). "Our experiment data further verified that LAS reduced PLK1 mRNA and protein expression in breast cancer, accompanied by downregulating CDC25C and AKT phosphorylation." (PMID 38495493, 2024). "Collectively, these studies underscore the therapeutic promise of combined targeting of PI3K and PLK1 pathways for combating therapy resistance and improving the clinical outcome of patients with advanced HR+ breast cancer." (PMID 39409880, 2024). "Consistent with this, the PLK1 protein was also significantly upregulated in the breast cancer cell lines (p < 0.05)." (PMID 38186570, 2023). "The expression of PLK1 is up-regulated in breast cancer, melanoma, non-small cell lung cancer, colorectal cancer, prostate cancer, pancreatic cancer, ovarian cancer, and other types of tumors." (PMID 38037110, 2023). "Recent studies have shown that PLK1 regulates the growth of breast cancer cells, and PLK1 inhibitors can be effective against BRCA." (PMID 38186570, 2023). "The aim of this study is to assess potential correlations between PLK1 expression and immune infiltration in breast cancer (BRCA) and construct a PLK1‐based immune risk model applicable for prognosis and treatment response prediction in BRCA." (PMID 36951624, 2023). "PLK1 expression was validated in diverse breast cancer cell lines by quantitative real-time polymerase chain reaction (qRT-PCR) and western blotting." (PMID 38186570, 2023). "In this study, we identified 8 cDEGs (COL11A1, COL10A1, CD36, ACACB, CD24, PLK1, UBE2C, and PDK4) as breast cancer (BC)-causing HubGs from 3 microarrays and one scRNA-seq dataset by the protein-protein interaction (PPI) network analysis of 46 cDEGs." (PMID 37893423, 2023).
breast carcinoma (continued). "The Michigan Cancer Foundation's (MCF) human breast cancer cells demonstrated significant inhibition of cell proliferation by targeting polo-like kinase 1 (PLK1) through this nanoformulation." (PMID 37108214, 2023). "A key regulator of these processes is Polo-like kinase 1 (PLK1), a proto-oncogene whose overexpression is frequently observed in tumor cells (among others colorectal cancer, lung cancer, breast cancer and melanoma)." (PMID 36768289, 2023). "PLK1 aberrantly overexpresses in a panel of cancer types such as breast cancer and prostate cancer, and was regarded as an ideal anti-cancer target." (PMID 37788997, 2023). "WTS8 and Bliss assays demonstrated that lowering the basal PLK1 expression in the breast cancer cell lines through miR-183-5p-mediated regulation would make them more sensitive to NMS-P937, resulting in a synergistic increase in apoptosis." (PMID 34561554, 2022). "Taken together, our study highlights CCNB1 and PLK1 as potential anti-breast cancer drug targets and prognostic markers." (PMID 35456460, 2022). "PLK1, an established oncogene in many cancers, is frequently overexpressed in glioma, colorectal cancer, breast cancer and in head and neck cancer." (PMID 35612714, 2022). "Both CCNE1 and PLK1 were highly expressed and were related to worse survival outcomes in breast cancer, indicating that they are suitable candidate targets for cancer treatment." (PMID 36393842, 2022). "This study shows the potential role of miR-183-5p as an onco-suppressor by inducing apoptosis through the downregulation of PLK1 and by synergically augmenting the apoptosis in breast cancer cells induced by NMS-P937." (PMID 34561554, 2022). "We selected the GEPIA2 database to analyze the expression of CCNB1 and PLK1 isoforms in breast cancer patients." (PMID 35456460, 2022). "To further explore the role of CCNB1 and PLK1 in the development of breast cancer, we used the GEPIA2 database to analyze the expression levels of CCNB1 and PLK1 at different clinical stages." (PMID 35456460, 2022). "Our work further elucidates how miR-183-5p regulates PLK1 gene while also enhancing NMS-P937 effect in breast cancer." (PMID 34561554, 2022). "Studies demonstrated the therapeutic value of PLK1 inhibition, particularly in endocrine‐resistant breast cancer, as overexpression of PLK1 is observed in the patient with cancer relapse." (PMID 36065138, 2022). "GSK461364 is thiophene amide, an ATP-competitor PLK1 inhibitor, which promotes G2/M arrest in tumor tissues; in addition, the drug enhanced the radio sensitivity of breast cancer cells in vivo." (PMID 35719948, 2022). "We analyzed the expression levels of their isoforms and found that the expression levels of CCNB1-001, CCNB1-003, CCNB1-006, and PLK1-001 in breast cancer tissues were higher than those in normal tissues." (PMID 35456460, 2022). "The goal of this study is to determine which miRNAs significantly regulate PLK1 expression via direct binding, and elucidate if this regulation affects breast cancer cells’ response to NMS-P937." (PMID 34561554, 2022). "PLK1 is overexpressed in various cancer, including breast cancer, non-small cell lung cancer, colorectal cancer, prostate cancer, pancreatic cancer, melanoma, ovarian cancer, non-Hodgkin’s lymphomas, and acute myeloid leukemia (AML)." (PMID 35256538, 2022). "The current study investigated the impact of PLK1 overexpression on disease prognosis in HR-positive early breast cancer (EBC) patients to demonstrate the PLK1 clinical relevance in HR-positive breast cancer." (PMID 35008374, 2022). "The results indicated three CCNB1 isoforms, including CCNB1-001, CCNB1-003, and CCNB1-006, and the isoform PLK1-001 of PLK1, were highly expressed in breast cancer samples." (PMID 35456460, 2022).
breast carcinoma (continued). "This being so, we were interested to explore the clinical relevance of PLK1 to patient survival in a cohort of breast cancer patient samples and found that high levels of PLK1 were associated with worse RFS, DMFS, and OS." (PMID 35454120, 2022). "In this study, we found that the hub genes CCNE1, PLK1, and SERPINA1 were significantly overexpressed, amplified, and mutated in breast cancer tissues compared with normal tissues." (PMID 36393842, 2022). "Such miRNA-driven regulation of PLK1 expression sensitizes breast cancer cells to NMS-P937, resulting in synergistically increased apoptosis." (PMID 34561554, 2022). "Researchers have shown the anti-sense inhibitors, that target PLK1 inducing a synergistic effect of taxane and paclitaxel, thereby enhancing the sensitivity of breast cancer cells to these drugs in vivo and in vitro." (PMID 35456460, 2022). "We then queried TCGA’s Invasive Breast Cancer Dataset (IBCD) for PLK1 and miR-183-5p expression, looking for possible anticorrelation in TNBC and Luminal A." (PMID 34561554, 2022). "PLK1 in interphase and mitosis has also been shown to play a significant role in promoting cell division in breast cancer cells." (PMID 35928368, 2022). "In the patients with specific breast cancer subtypes, PLK1 overexpression was correlated with improved survival." (PMID 36267311, 2022). "Current studies have found that PLK1 is highly expressed in a variety of tumors, including breast cancer, colorectal cancer, endometrial cancer, ovarian cancer, pancreatic cancer, and non-small-cell lung cancer." (PMID 35909589, 2022). "We then examined mRNA expression in the TCGA database to further investigate the relationship between PLK2 and PLK1 in breast cancer." (PMID 35156101, 2021). "Our results show that PLK1 was specifically highly expressed in Basal-subtype breast cancer, and was mainly enriched in the cell cycle, mitosis and chromosome segregation pathways." (PMID 33644115, 2021). "PLK1 participated in the process of neuronal autophagy and decreased the expression of PLK1 will indirectly inhibit mitophagy of breast cancer cells." (PMID 34115550, 2021). "The mechanistic evaluation of such an activity carried out using in silico methods suggested that the anti-breast cancer activity of L-ZnONPs was mediated by polo-like kinase 1 (PLK1) proteins." (PMID 33807771, 2021). "Here, we demonstrated that PLK2 functions as a tumor suppressor in breast cancer, and suggested that its tumor-suppressive role is mediated, at least partially, by its direct interaction with PLK1." (PMID 35156101, 2021). "With respect to breast cancer development, a tumor suppressor function of PLK1 has been confirmed in a Plk1 gain of function mouse model using an inducible knock-in-setting." (PMID 34065956, 2021). "PLK1 is overexpressed in breast cancer, especially TNBC, and targeting PLK1 has been reported to impair TNBC growth." (PMID 35156101, 2021). "Our data have revealed that L1 is effective in reducing cell viability in three breast cancer cell lines and that there are significant synergistic effects between L1 and the Plk1 inhibitor, BI2536." (PMID 34493069, 2021). "Many researchers have demonstrated that PLK1 is highly expressed in various tissues for tumor, such as breast cancer, ovarian cancer, and prostate cancer." (PMID 33313822, 2021). "This indicated that the dysregulation of the PLK1 signaling pathway contributed to the prognosis of breast cancer patients." (PMID 34513664, 2021). "Such a kinase, named PLK1 (polo-like kinase 1) communicates with ER-α and modulates the transcription of ER-α target genes in breast cancer cells." (PMID 33777765, 2021). "LUT is able to reverse EMT of MDA-MB-231- and BT5-49-mediated breast cancer cells and inhibits PLK1 gene expression in MCF-7 breast cancer." (PMID 34452179, 2021).